UCP2 (uncoupling protein 2)
Diseases named in the same sentence as UCP2 in open-access papers (continued):
Sharing a sentence is not in itself a finding about the gene and the disease.
hepatocellular carcinoma (15 papers, 2010 to 2025). A malignant tumor that arises from hepatocytes. "Results demonstrated that UCP2 was associated with autophagy during PA-induced hepatic carcinoma cells injury." (PMID 25512910, 2014). "For example, the UCP2 transcript is post-transcriptionally downregulated by miR-214 in normal hepatic cells, and miR-214 expression is significantly downregulated in hepatocellular carcinoma patient samples." (PMID 34199098, 2021). "Direct effects of hesperidin and capsaicin, individually and in combination, on mRNA of Trpv1 and Ucp2 were assessed in vitro in the human hepatoma-derived cell line HepG2." (PMID 30305645, 2018). "Overexpression of UCP2 decreased intracellular ROS and attenuated apoptosis in HepG2 hepatoma cells induced by various challenges." (PMID 26666173, 2015). "Overall, we have demonstrated that UCP2 protects hepatic carcinoma cells from PA-induced apoptosis in vitro by increasing hepatocyte autophagy." (PMID 25512910, 2014). "To further confirm these results, we altered UCP2 expression levels in H4IIE hepatoma cells by transfection with either an UCP2 mRNA interference (siRNA) plasmid or a UCP2-overexpressing plasmid." (PMID 25512910, 2014). "We predict that the antiapoptotic effect of UCP2 most likely relates to its preventative role in its inductive effect of hepatoma autophagy." (PMID 25512910, 2014). "This study aims to investigate the relationship between UCP2 and hepatoma cells autophagy in palmitic acid- (PA-) induced lipotoxicity." (PMID 25512910, 2014). "Supportive evidence comes from ectopic expression experiments, in which HepG2 human hepatoma cells overexpressing UCP2, reduced oxidative stress and increased resistance to apoptosis induced by menadione or hypoxia/ reoxygenation." (PMID 24281083, 2010). "Furthermore, PA has been shown to mediate autophagy in hepatoma cells through the regulation of mitochondrial uncoupling protein 2 (UCP2) expression." (PMID 37637038, 2023). "Moreover, it was published that UCP-2 silencing in human hepatocellular carcinoma (HepG2) cells decreases lactate production and increases the ATP:ADP ratio, indicating that UCP-2 favors glycolytic pathways." (PMID 32120777, 2020). "In conclusion, increasing UCP2 expression in hepatoma cells may contribute to cell autophagy and antiapoptotic as result of fatty acid injury." (PMID 25512910, 2014). "In this study, the hepatocellular carcinoma Hep3B and HepG2 cells and colorectal cancer HT-29 cells were treated with 5-azacytidine (5-aza), a DNA demethylation agent, to observe the modification of UCP2 expression and the methylation degree in the UCP2 promoter region." (PMID 33859525, 2021). "Increasing UCP2 expression in hepatoma cells may contribute to cell autophagy." (PMID 25512910, 2014). "Moreover, UCP2 could enhance hepatoma autophagy, such that UCP2-mediated autophagy induced by PA was first found to serve as an antiapoptotic mechanism to oppose the lipotoxic effects." (PMID 25512910, 2014). "UCP2 is found to be overexpressed in hepatocellular carcinoma (HCC) and colon cancer." (PMID 27129291, 2016). "Results revealed that the UCP2 mRNA and protein levels were both increased in H4IIE cells treated with 250 μM PA for 6 h compared to the vehicle control, suggesting that the upregulation of UCP2 expression is mediated by PA in hepatoma cells." (PMID 25512910, 2014). "Consistent with the in vivo data, the UCP2 expression in hepatoma cell H4IIE and macrophage cell RAW 264.7 was not affected by adiponectin." (PMID 22359684, 2012). "The effects of IGF-1 on complex V expression may be a compensatory response to mitochondrial uncoupling as IGF-1 induces uncoupling protein 2 (UCP2) expression through the PI3K/AKT/FOXO1 axis in diverse cell types including mouse adipocytes, myoblasts, and human hepatocellular carcinoma cells." (PMID 39433211, 2025).
cardiac hypertrophy (12 papers, 2013 to 2025). "In contrast, in models of cardiomyopathy induced by chronic β-adrenergic signaling, the cardiac hypertrophy was associated with upregulation of UCP2." (PMID 23825553, 2013). "In agreement with this, we observed that levels of the natriuretic peptide precursor type A (Nppa), one of most commonly used marker of cardiac hypertrophy tripled in mtDNA mutator hearts after UCP2 depletion highlighting a progression of mitochondrial dysfunction in DM mice." (PMID 24945157, 2014). "ECH macrophages also exhibited an induction of Ucp2 (mitochondrial uncoupling protein 2), that plays a cardioprotective role in cardiac hypertrophy promoting mitochondrial fission, ATP synthesis and a decreased ROS production." (PMID 35203431, 2022). "The current study aims to clarify the role of UCP-2 during the transition from cardiac hypertrophy to heart failure." (PMID 32120777, 2020). "Increased UCP2 has been correlated with reduced cardiac efficiency in cardiac hypertrophy in hyperthyroidism." (PMID 29576853, 2018). "As a main result we found that AGAT−/− mice exhibited altered gene expression related to energy metabolism (Fbp2, Ucp2), cardiac hypertrophy and fibrosis (Nppa, Ctgf), immune response (Fgl2), and the conduction system of the heart (Dsc2, Ehd4, Hcn2, Hcn4, Scn4a, Scn4b)." (PMID 32179820, 2020). "Interestingly, the mRNA expression of PGC-1α, associated with mitochondrial formation increased in the early, adaptive phase of cardiac hypertrophy, but declined thereafter, when the expression of UCP-2 was induced and function worsened." (PMID 32120777, 2020). "Having successfully established an in vitro model to study the effects of UCP-2 in isolated heart muscle cells by small interfering RNA, we proceeded to identify potential mechanisms by which UCP-2 may affect cardiac hypertrophy and failure." (PMID 32120777, 2020). "The overexpression of UCP2 in neonatal rat cardiomyocytes protected the cells from oxidative stress-mediated damage, and activation of the AMPK/UCP2 pathway protected from indoxyl sulfate-induced cardiac hypertrophy and oxidative stress in isolated cardiomyocytes." (PMID 40427496, 2025). "However, another study using UCP2 inhibitor genipin and Ucp2-/- mice showed that inhibition of UCP2 attenuates cardiac hypertrophy induced by transverse aortic constriction without affecting blood pressure in mice." (PMID 30116205, 2018).
pancreatic adenocarcinoma (12 papers, 2013 to 2024). "The loss of UCP2 in different human pancreatic adenocarcinoma cell lines further stimulated autophagy through the ROS-dependent nuclear translocation of glyceraldehyde-3-phosphate dehydrogenase (GAPDH)." (PMID 36499405, 2022). "In pancreatic adenocarcinoma, the combination of UCP2 inhibitor genipin and mTOR inhibitor everolimus results in synergistic suppression of cancer cell growth and induction of cell apoptosis." (PMID 38217303, 2024). "UCP2 inhibitor genipin can suppress growth of pancreatic adenocarcinoma cells and trigger cell apoptosis via promoting GAPDH nuclear translocation." (PMID 38217303, 2024). "In pancreatic adenocarcinoma, UCP2 inhibition strongly increases ROS production and induces autophagy, which inhibits cell growth and triggers ROS-dependent cell death." (PMID 37744277, 2023). "Correlatively, the transfection of Ucp2 siRNA into A549 and PaCa44 (human pancreatic adenocarcinoma) cell lines inhibited cell growth through a strong increase in ROS production." (PMID 36499405, 2022). "Prooxidative state established by genipin blockage of UCP2 retarded pancreatic adenocarcinoma cell growth and, in contrast, UCP2 overexpression diminished basal autophagy." (PMID 29351723, 2018). "In their study, employing mice xenografts of pancreatic adenocarcinoma and in vitro experiments, inhibition of UCP2 by genipin triggered the Akt/mTOR pathway by a ROS-dependent mechanism." (PMID 29587429, 2018). "The results of this study support the use of UCP2 inhibitors in anti-tumor strategies for the treatment of pancreatic adenocarcinoma and provide novel insight into the structure of GNP." (PMID 26771380, 2016). "Since gentamycin alone induces Ucp2 gene expression in pancreatic adenocarcinoma cell lines, it has been hypothesized that UCP2 is directly involved in acquired cancer resistance to gentamycin." (PMID 36499405, 2022). "UCP2 inhibition may induce pancreatic adenocarcinoma cell death by increasing reactive oxygen species (ROS) levels." (PMID 26771380, 2016). "In addition, in pancreatic adenocarcinoma, non-small cell lung adenocarcinoma, and bladder carcinoma cell lines IC50 values of the anticancer drug gemcitabine increase with intrinsic UCP2 mRNA abundance." (PMID 23966948, 2013).
coronary artery disease (11 papers, 2009 to 2025). "In contrast a study of 3122 type-2 diabetic patients reported association of the UCP2 -866 A allele with decreased risk of incident coronary artery disease, including sudden cardiac death." (PMID 19527523, 2009). "It was reported that UCP2 expression alters differently in the settings of coronary artery disease and myocardial ischemia." (PMID 35284500, 2021). "By shedding light on the role of the TRPV6/PKA/UCP2 pathway in inhibiting inflammatory response and cell apoptosis in coronary atherosclerotic plaques, this study provides valuable insights into potential therapeutic targets for treating coronary artery disease (CAD)." (PMID 39742020, 2024). "UCP2 expression alters in the settings of coronary artery disease (CAD) and myocardial ischemia." (PMID 30116205, 2018). "However, in contrast to patients with idiopathic dilated cardiomyopathy (DCM) and ischemic heart disease (IHD), patients with mitochondrial cardiomyopathy (MIC) have increased expression of genes involved in fatty acid metabolism, including Ucp2, Cpt1, Pparα and Pgc1-α." (PMID 24945157, 2014).
heart failure (10 papers, 2011 to 2024). Inability of the heart to pump blood at an adequate rate to meet tissue metabolic requirements. "Overexpression of UCP2 in the heart after MI ameliorates heart failure and reduces myocardial fibrosis and apoptosis." (PMID 35284500, 2021). "In UCP-2 knockout mice, heart failure induced by acute pressure overload was attenuated and cardiac function preserved." (PMID 32120777, 2020). "This suggests a potential role for UCP-2 at the transition from cardiac adaptation to heart failure." (PMID 32120777, 2020). "The cardiac expression of the mitochondrial uncoupling protein (UCP)-2 is increased in patients with heart failure." (PMID 32120777, 2020). "Results from our in vitro and in vivo experiments suggest that upregulation of UCP-2 and a corresponding down-regulation of Glut-4 participate in the progression of heart failure under conditions of chronic pressure overload." (PMID 32120777, 2020). "UCP2 is decreased in both animal models and patients with heart failure, allowing a rational approach of overexpressing UCP2 in an attempt to ameliorate heart failure." (PMID 30116205, 2018). "In animal model of heart failure induced by pressure overload induced by constriction of the ascending aorta, the expression of UCP2 and UCP3 is downregulated and an increase of ROS generation is enhanced to induce cardiac cell hypertrophy." (PMID 27642497, 2016). "Since cytosolic Ca2+ overload is considered as unfavorable and is observed in the onset of heart failure, compensatory mechanisms in UCP2-/- mice are likely." (PMID 26849136, 2016). "Recently, UCP2 was shown to be upregulated in an aortic regurgitation model of heart failure, and UCP3 upregulation and mitochondrial uncoupling were demonstrated in viable myocardium of chronically infarcted, failing rat hearts." (PMID 22125598, 2011). "However, in this study, it is found proper external supply of UCP2 protected against heart failure after MI." (PMID 35284500, 2021). "Therefore, we studied in vitro and in vivo the expression of UCP-2 in rat cardiomyocytes and its effects on left ventricular (LV) remodeling in terms of functional and metabolic reactions during the transition to heart failure." (PMID 32120777, 2020). "For this reason, UCP-2 inhibition might be a promising therapeutic strategy to prevent the development of heart failure." (PMID 32120777, 2020). "However, super-induction of UCP2 occurs at the time of transition to heart failure." (PMID 39167912, 2024). "Finally, we addressed the question of whether a similar effect of UCP-2 and Glut-4 expression holds in human hearts at end-stage heart failure." (PMID 32120777, 2020). "Heart failure results in a decrease in Ucp2 and Ucp3, though it is unknown whether the change in these proteins is beneficial or detrimental to the failing heart; however, an increase in the expression of UCPs in cardiac mitochondria decreases free radical production." (PMID 33287280, 2020).
insulinoma (10 papers, 2007 to 2021). "In similar experiments with mitochondria isolated from tissues rich in UCP2 and insulinoma INS-1E cells, the antioxidant synergy of UCP2 plus iPLA2γ was demonstrated being dependent on the identified redox activation of iPLA2γ." (PMID 33926059, 2021). "They showed that MGO induces the activation of uncoupling protein 2 (UCP-2) in mouse insulinoma (MIN-6) cells, resulting in reduced mitochondrial membrane potential and ATP production, which can suppress glucose-stimulated insulin secretion." (PMID 31331077, 2019). "We have reported previously that knockdown of UCP2 by RNAi leads to improved GSIS in INS-1E insulinoma cells." (PMID 21172424, 2011). "In the present paper we characterise the content and regulation of UCP2 in INS-1E insulinoma cells, a widely used clonal rat pancreatic beta-cell model." (PMID 18692019, 2008). "The two procedures used to assay the activity of the UCP2 mutants, expression in yeast or expression in insulinoma cells, were previously used by us and others." (PMID 19065272, 2008). "The UCP2 antioxidant cytoprotection has been documented in detail for insulinoma INS1E cells." (PMID 29351723, 2018). "To assess whether the modification of UCP2 activity observed in patients 1 and 2 could affect insulin secretion in beta cells, we subjected an insulin-secreting pancreatic insulinoma cell line (INS-1E) to adenoviral expression of wild type and mutated UCP2 in mitochondria." (PMID 19065272, 2008). "UCP2 content, measured by calibrated immunoblot in INS-1E insulinoma cells (a pancreatic beta-cell model) grown in RPMI medium, and INS-1E mitochondria, was 2.0 ng/million cells (7.9 ng/mg mitochondrial protein)." (PMID 18692019, 2008). "Although caution is due when inferring physiological meaning from insulinoma cell data, our results would suggest UCP2 does not mediate harmful effects of palmitate in beta cells and does not protect against such effects either." (PMID 25482405, 2015). "By measuring mitochondrial bioenergetics in attached INS-1E insulinoma cells with and without UCP2, we show that UCP2 contributes to proton leak and attenuates glucose-induced rises in both respiratory activity and the coupling efficiency of oxidative phosphorylation." (PMID 21172424, 2011).
nonalcoholic fatty liver disease (9 papers, 2012 to 2025). "Of all known UCPs, UCP2 has the highest level in liver but previous researches were mainly focusing on its association with nonalcoholic fatty liver disease, in the aspects of both expression change and gene polymorphisms." (PMID 28969071, 2017). "Further studies with larger sample size and interventional designs are needed to determine the association of dietary compounds and different UCP2 genotypes in nonalcoholic fatty liver disease." (PMID 27301474, 2016). "The UCP2 protein expression has been linked to the occurrence of nonalcoholic fatty liver disease." (PMID 23151243, 2012). "Activation of TRPV1/UCP2 axis by capsaicin has been reported in several disease models, including nonalcoholic fatty liver disease and diabetic cardiovascular complications." (PMID 37528882, 2023). "It has been suggested that UCP2 has a role in the development of nonalcoholic fatty liver disease (NAFLD)." (PMID 25512910, 2014). "For example, in another report, BBR decreased the expression level of UCP2 in the liver in a rat model of nonalcoholic fatty liver disease (NAFLD) and reduced hepatic steatosis." (PMID 24669227, 2014). "Rosiglitazone elicits its protective functions against non-alcoholic fatty liver disease largely through the induction of adiponectin, which prevents mitochondria stresses by promoting GSK3beta activation and UCP2 upregulation, two pathways coordinating the glucose and lipid metabolism in liver." (PMID 25375187, 2014). "For example, in a model of nonalcoholic fatty liver disease, LB100 regulated UCP2 expression by inhibiting AMPK." (PMID 38568919, 2024).
diabetic retinopathy (8 papers, 2014 to 2025). "In an attempt to obtain more direct evidence for the involvement of UCP2 in diabetic retinopathy, several groups have carried out GWAS studies and have identified a significant linkage between several UCP2 polymorphisms and the diabetic retinopathy phenotype." (PMID 35628482, 2022). "Upregulation of UCP2 expression by treatment of perindopril has been shown to rescue attenuated mitochondrial membrane potential in a rat model of diabetic retinopathy." (PMID 40078371, 2025). "While the link between a factor that effectively treats diabetic retinopathy and the expression of UCP2 is currently only a strong correlation, it does argue for one avenue developing new therapeutics for this disease." (PMID 35628482, 2022). "While UCP2 is clearly not the major cause of diabetic retinopathy, it seems to play an important role in the disease progression." (PMID 35628482, 2022). "Since UCP2 plays a role in reducing the production of ROS, selective activation of UCP2 may have therapeutic potential in patients with diabetic retinopathy." (PMID 36009191, 2022). "Taking into consideration the role of UCP2 in the protection against oxidative stress, our group previously investigated whether the UCP2 -866G/A, Ala55Val and Ins/Del polymorphisms, also described in association with T2DM, could be also associated with diabetic retinopathy (DR)." (PMID 26218518, 2015).